PACS1 (phosphofurin acidic cluster sorting protein 1)
Diseases named in the same sentence as PACS1 in open-access papers (continued):
Sharing a sentence is not in itself a finding about the gene and the disease.
tumor (5 papers, 2018 to 2025). "Phosphofurin acidic cluster sorting protein 1 (PACS1) is a tumor-suppressor that regulates intrinsic (mitochondrial) apoptosis with its partner ADA3." (PMID 33193605, 2020). "Given that the pro-apoptotic proteins PCAF, ADA3, and PACS1 were significantly down regulated in tumor compared to premalignant gastric mucosa at the mRNA level, we examined the expression of the corresponding proteins by immunohistochemistry in a tissue microarray (TMA)." (PMID 29670108, 2018). "PACS1 expression is shown to be consistently higher in both in-house and TCGA CRC tumor samples, as well as pre-surgical cfRNA." (PMID 37091184, 2023). "Our analysis shows a significant correlation between PACS1 and HPGD expression levels post-operation, suggesting that PACS1 may act to regulate the HPGD expression in response to changes within the tumor microenvironment." (PMID 40728977, 2025). "CDCA7, CELSR3, PACS1, SNTB1, and TBC1D31 showed consistent upregulation in CRC tumor samples and pre-surgical cfRNA, while GFI1B, HPGD, SH3BGRL2, SIAE, PKHD1L1, and TDP2 showed downregulation in CRC tumor samples and pre-surgical cfRNA." (PMID 37091184, 2023). "We set out to validate the expression of the three cfRNA biomarkers – HPGD, PACS1, and TDP2 identified in our in-house cfRNA and CRC tissue samples using an independent cohort of pre- and post-surgical cfRNA samples (N=36) and published TCGA CRC tumor and tumor-adjacent samples (N=453)." (PMID 37091184, 2023).
autosomal dominant disease (3 papers, 2022 to 2025). Autosomal dominant form of disease. "The Schuurs–Hoeijmakers syndrome (SHMS) or PACS1 Neurodevelopment Disorder (PACS1-NDD) is a rare autosomal dominant disease caused by mutations in the PACS1 gene." (PMID 36077045, 2022).
genetic disorders (2 papers, 2022 to 2025). "Overall, our results confirm the presence of consistent facial similarities among PACS1-, PACS2-, and WDR37-related syndromes and highlight the utility of AI-driven facial phenotyping as a complementary tool for uncovering clinically relevant relationships in ultra-rare genetic disorders." (PMID 40869285, 2025).
infection (2 papers, 2015 to 2023). The state of being infected such as from the introduction of a foreign agent such as serum, vaccine, antigenic substance or organism. "Indeed, the Nef/PACS-1 interaction modulates the downregulation of cell surface MHC-I via a mechanism that depends on the length of infection." (PMID 25915798, 2015). "Only HPGD, PACS1, and TDP2 showed involvement in biological pathways, including metabolism, infection, and DNA repair-related pathways." (PMID 37091184, 2023).
Heart Disease (1 paper, 2023). "Heart disease (HD) is frequently present in individuals with PACS1-NDD, but a compressive review of these anomalies and an evaluation of cardiac function in a cohort of patients are lacking." (PMID 37373745, 2023).
myopathy (1 paper, 2022). A disease of the muscle in which the muscle fibers do not function properly. "Forty-six candidate genes are prioritized by multiple approaches (42 for LST and 6 for MVPA; 2 overlap) and point to endocytosis (CNIH2, RAB1B, KLC2, PACS1, REPS1, DNM3, EXOC4), locomotion (CADM2, KLC2) and myopathy (MLF2, HERC1, KLC2, SIL1) as relevant pathways." (PMID 36071172, 2022).
neurological disorder (1 paper, 2025). "Recent work revealed strong similarities between PACS1-NDD, PACS2 syndrome and the recently identified WDR37 syndromic neurological disorder." (PMID 39999877, 2025).
PACS1 also shares sentences with these, for which no sentence is quoted: developmental delay (6 papers); Seizure (3); cervical cancer (2); microcephaly (2); acquired immune deficiency syndrome (1); adrenoleukodystrophy (1); autism (1); autism spectrum disorder (1); biotinidase deficiency (1); bipolar disorder (1); breast carcinoma (1); chronic gastritis (1); colorectal cancer (1); Corneal opacity (1); cryptorchidism (1); Down syndrome (1); endocrine disorders (1); Epileptic encephalopathy (1); Failure to thrive (1); gastric tumor (1); gastrointestinal disorders (1); Hartnup disease (1); maple syrup urine disease (1); metabolic disorders (1); metachromatic leukodystrophy (1); musculoskeletal disorders (1); speech delay (1); type I citrullinemia (1).